DSG3 (desmoglein 3)
Diseases named in the same sentence as DSG3 in open-access papers (continued):
Sharing a sentence is not in itself a finding about the gene and the disease.
autoimmune disease (32 papers, 2006 to 2025). A disorder resulting from loss of function or tissue destruction of an organ or multiple organs, arising from humoral or cellular immune responses of the individual to their own tissue constituents. "Pemphigus Vulgaris (PV) is a life-threatening autoimmune disease manifested with blisters in the skin and mucosa and caused by autoantibodies against adhesion protein desmoglein-3 (Dsg3) expressed in epithelial membrane linings of these tissues." (PMID 33968042, 2021). "On the other hand, DSG3 is also expressed in normal squamous epithelium, and autoantibodies against DSG3 cause PV, an autoimmune disease that includes severe skin lesions, such as blistering." (PMID 30239818, 2018). "Pemphigus Vulgaris is an autoimmune disease that results in blister formation in the epidermis and in mucosal tissues due to antibodies recognizing desmosomal cadherins, mainly desmoglein-3 and -1." (PMID 31247885, 2019). "It is well-known that PV and BP are autoantibody-driven autoimmune disorders in which both T cells and B cells with auto-reactivity towards DSG3 and BP180/BP230, respectively, are necessary for their pathogenesis." (PMID 25644263, 2015). "Although it has been well established that DSG3 plays a key role in the development of PV, less is known about a potential role of desmocollins in autoimmune diseases." (PMID 20585602, 2010). "PV is an autoimmune disease characterized primarily by the presence of IgG antibodies against Dsg1 and Dsg3 due to the involvement of immune responses mediated by B cells (crucial to producing specific autoantibodies) and T cells (participating in the onset and persistence of PV)." (PMID 40649854, 2025). "The dysfunction in suppressing proinflammatory cytokine secretion and Birc5 upregulation in Dsg3-specific autoreactive T cells may reflect an aspect of the preliminary steps in autoimmune disease development in the aged population." (PMID 37308897, 2023). "While it remains unclear how Dsg3-specific mAbs develop, evidence from other autoimmune diseases such as lupus suggest that autoantibodies develop prior to disease onset, and accumulation of autoantibodies ultimately drive disease pathogenesis." (PMID 31340153, 2019). "This has raised the concern the binding of unrelated antibodies to Dsg-proprotein could lead to false positive detection of anti-Dsg3 or 1 antibodies, as has been shown for anti-Dsg1 in healthy controls and patients with the unrelated autoimmune disease thrombotic thrombocytopenic purpura." (PMID 36211362, 2022). "Finally, we evaluated whether this pathway was operational in the autoimmune disease PV in which Dsg3 serves as a major antigen involved in blistering pathogenesis." (PMID 31582719, 2019). "As regards PV, the HLA selective presentation of DSG3 peptides in PV has been thoroughly analyzed, starting from the premise that peptide presentation to T cells may be important in the initiation or progression of autoimmune diseases." (PMID 17062151, 2006). "PV is an autoimmune disease with autoantibody development against the desmosomal cadherins DSG1 and DSG3, resulting in blister formation in the skin and oral mucosa." (PMID 41037786, 2025). "Dsg3-specific cells expressed the classical MBC marker CD27, excluding these cells from the atypical IgD-CD27− MBCs described in other autoimmune diseases." (PMID 31340153, 2019). "Around the same time, it was shown that patients who suffer from autoimmune diseases characterized by skin and mucous membrane blistering produce autoantibodies against desmogleins 1 and 3 (DSG1, DSG3)." (PMID 20885972, 2010). "The Dsg3 null mice do not develop an autoimmune disease; that is, they do not provide us with a tool to dissect autoantibody-mediated pathology." (PMID 20585602, 2010).
pemphigus foliaceus (31 papers, 2010 to 2024). Pemphigus foliaceous is a rare superficial pemphigus disease characterized by multiple, pruritic, scaly, crusted cutaneous erosions, with flaky circumscribed patches, localized mostly on the face, scalp, trunk and extremities, often presenting an erythematous base. "Different expression patterns of Dsg3 and Dsg1 give rise to either the mucosal-dominant PV (Dsg3) or the primarily skin-associated pemphigus foliaceus (PF; Dsg1)." (PMID 36203615, 2022). "Mucosal-dominant pemphigus vulgaris (PV) is characterised by autoantibodies (PV-IgG) against Dsg3 whereas epidermal blistering in PV and pemphigus foliaceus (PF) is associated with autoantibodies against Dsg1." (PMID 34434944, 2021). "It is now known that pemphigus foliaceus (PF) is characterized by autoantibodies to desmoglein (Dsg) 1 and pemphigus vulgaris (PV) is characterized by autoantibodies to Dsg3, although 60% of PV sera also contain Dsg1 autoantibodies." (PMID 36013115, 2022). "In the pemphigus foliaceus (PF) subgroup, only antibodies against Dsg1 are present, whereas in pemphigus vulgaris (PV) antibodies against Dsg3 are found in mucosal dominant PV (mdPV), or together with anti-Dsg1 in mucocutaneous PV (mcPV)." (PMID 29740444, 2018). "DSG3 provide desmogleing compensations with DSG1 in pemphigus foliaceus (PF), which is a potentially fatal autoimmune blistering skin disease in which autoantibodies against DSG3 and DSG1 cause loss of keratinocyte cell adhesion." (PMID 30510564, 2018). "In pemphigus foliaceus (PF), patients develop pathogenic autoantibodies that target Dsg1 and promote cell-cell disadhesion in the superficial epidermis, where Dsg1 is highly expressed, but which lacks Dsg3 and Dsg2." (PMID 20631906, 2010). "The autoantibody profiles with either anti-Dsg1 or anti-Dsg1 and anti-Dsg3 IgG largely correlate with the clinical phenotypes of pemphigus foliaceus (PF) or pemphigus vulgaris (PV) respectively." (PMID 39882246, 2024). "Anti-DSG3 antibodies (Abs) are observed in pemphigus vulgaris (PV) with mucosal involvement, and anti-DSG1 Abs are observed in patients with pemphigus foliaceus (PF) and those with PV and skin involvement." (PMID 31440235, 2019). "Pemphigus foliaceus (PF) is characterized by autoantibodies against desmoglein (DSG) 1, while DSG3 autoantibodies are characteristic of mucosal pemphigus vulgaris (PV), and reactivity against both autoantigens is seen in mucocutaneous PV." (PMID 35330080, 2022). "Clinically, the initial severity of pemphigus foliaceus (PF) and PV is correlated with anti-DSG1 and anti-DSG3 Ab serum levels, respectively." (PMID 35371083, 2022). "Pemphigus foliaceus (PF) is an autoimmune blistering disease characterized by superficial blisters due to the autoantibody-mediated disruption of the epidermal cell adhesion protein desmoglein 1 (DsG1) and not desmoglein 3 (DsG3)." (PMID 39734965, 2024).
squamous cell carcinoma (16 papers, 2010 to 2024). A carcinoma arising from squamous epithelial cells. "In accordance with this notion, other studies have independently implicated that DSG3 plays a role in cancer as it is found to be upregulated in squamous cell carcinomas (SCCs) although the function of DSG3 in tumor cell biology remains an area poorly defined." (PMID 34206820, 2021). "Similar to our findings in this study, EGFR inhibition has been shown to increase cellular cohesion in squamous cell carcinomas, whereas in keratinocytes, EGFR inhibition protected against DSG3 autoantibody–induced loss of keratinocyte adhesion." (PMID 36795511, 2023). "Alterations in DSG3 expression have also been observed in squamous cell carcinoma (SCC) in multiple organ systems." (PMID 38067138, 2023). "Desmoglein-3 (DSG3) is expressed in normal squamous epithelia and overexpressed in squamous cell carcinoma (SCC) of the lung." (PMID 30239818, 2018). "Paradoxically, up-regulation of Dsg3 recently has been reported in squamous cell carcinoma and pre-malignant inverted papilloma." (PMID 21151980, 2010). "By validating the expression profiles of six specific genes (MIR205HG, KRT5, KRT6A, KRT6C, SERPINB5, and DSG3), selected based on a previously established 53-gene signature, we consistently observed higher expression levels in squamous cell carcinoma (SCC) compared to adenocarcinoma (ADC)." (PMID 38612418, 2024). "Moreover, a recent comprehensive study based on 15,869 tissue microarrays identified that DSG3 expression is predominant in squamous cell carcinomas." (PMID 38067138, 2023). "The same analogy could apply to DSG3 as it has been identified as a pro‐survival protein and biomarker in squamous cell carcinoma." (PMID 35000271, 2022). "Moreover, results from microarray-based studies have led to the identification of upregulated expression levels of the DSG3 gene in squamous cell carcinoma." (PMID 31877723, 2019). "DSG3 is overexpressed in squamous cell carcinoma and head and neck cancer, and abnormal expression of DSG2 in melanoma, squamous cell carcinoma, and gastric cancer has also been reported." (PMID 32498335, 2020). "Overexpression of CFBF, PAGE2, CALM3, DSG3, CTAG2, and FAM83C was seen only in squamous cell carcinoma." (PMID 31877723, 2019).
Autoimmunity (15 papers, 2006 to 2025). The occurrence of an immune reaction against the organism's own cells or tissues. "This etiology of APS1/APECED B cell autoimmunity is strikingly similar to proposed origins of highly mutated anti-desmoglein-3 antibodies in autoimmune pemphigus and of anti-GM-CSF antibodies pathognomonic in pulmonary alveolar proteinosis." (PMID 27426947, 2016). "As positive controls to validate our epitomic approach, we also measured binding of PV AuAbs to the ES for Dsg1 and Dsg3 epitopes, which are well-known targets of PV autoimmunity." (PMID 40120680, 2025). "We previously generated a Dsg-3-specific TCR transgenic mouse, Dsg3H1, which was used to demonstrate that CD4+ helper T cells are crucial for autoantibody production and to examine the pathomechanism of anti-Dsg3 autoimmunity." (PMID 37308897, 2023). "This review focuses on the research investigating T cell autoimmunity and immune regulation induced by Dsg3." (PMID 36539957, 2023). "JNK is among a number of pathways that are triggered by PV‐IgG; anti‐Dsg3 antibodies in PV autoimmunity are for the most part related to signaling events regarding both JNK and p38MAPK." (PMID 35616233, 2022). "In the early stage of disease, patients demonstrate autoimmunity only to Dsg3 and develop mucosal blisters; while at the later stage, patients exhibit non-cross-reactive immunity to both Dsg3 and Dsg1." (PMID 17254312, 2006).
head and neck cancer (10 papers, 2012 to 2023). A primary or metastatic malignant neoplasm affecting the head and neck. "Consistent with other reports, we have previously found that DSG3 functions as an oncogene in head and neck cancer and is associated with advanced clinical stage." (PMID 23737966, 2013). "Most head and neck cancers expressing elevated levels of desmoglein 3 (DSG3) metastasize to the neck lymph nodes." (PMID 34490084, 2021). "Previous studies have demonstrated that DSG3 is an accurate biomarker for staging sentinel lymph nodes in head and neck cancer, and for distinguishing lung squamous cell carcinoma from other subtypes of lung cancer." (PMID 32081836, 2020). "DSG3 has been reported to be overexpressed in head and neck cancers and this has been correlated with lymph node metastasis and cell proliferation." (PMID 26700817, 2016). "In all, these results supported our molecular findings that DSG3 functions as an oncogene in head-neck cancer through the DSG3-plakoglobin-CF/LEF - myc/cyclinD3/MMP signaling pathway." (PMID 23737966, 2013). "An oncogenic role for DSG3 is further supported by in vitro experiments showing that DSG3 knockdown inhibits tumor growth and invasion in various head and neck cancer cell lines and impairs epithelial cell proliferation." (PMID 23185521, 2012). "Additionally, DSG3 was previously found to be overexpressed at both the RNA and protein levels in head and neck cancer." (PMID 37835579, 2023). "The decrease of DSG1, DSC2, DSC3, DSG3, PG, PKP1-3, and DSP expression associated with poor prognosis in patients with multiple cancers such as head and neck cancer, colon cancer, skin cancer, esophageal cancer, lung cancer, cervical cancer, and gastric cancer." (PMID 34203070, 2021). "DSG3 is overexpressed in head and neck cancer, where it functions as an oncogene." (PMID 32081836, 2020). "Previously, an oncogenic function of DSG3 has been found in head neck cancer (HNC)." (PMID 23737966, 2013). "However, over-expression of DSG2 or DSG3 has also been shown in several cancers including skin, prostate, lung and head-neck cancer." (PMID 23737966, 2013). "This study provides evidence that DSG3 could potentially serve as a molecular target for chemotherapeutic agents in the treatment of head and neck cancer." (PMID 23737966, 2013).
lung carcinoma (9 papers, 2017 to 2025). "This agrees with previous reports that associated positive DSG3 staining with longer survival in lung cancer patients of all histologic subtypes." (PMID 31809668, 2020). "Desmoglein 3 (DSG3) is underexpressed in lung cancer, and a lower expression of DSG3 is significantly linked to higher tumor grade." (PMID 29855376, 2018). "DSG3 protein expression in lung cancer patients was assessed using IHC, and its impact on prognosis was analyzed in the TCGA database." (PMID 38900156, 2024). "This interaction culminates in the establishment of a transcriptional complex that governs the expression of DSG3, subsequently influencing the invasive phenotype of lung cancer cells through the Ezrin pathway." (PMID 38900156, 2024). "The effects and mechanisms of DSG3 on lung cancer phenotypes were assessed through WB, transwell, and wound healing assays." (PMID 38900156, 2024). "Furthermore, TCGA data underscored a correlation between elevated DSG3 expression and poorer prognosis in lung cancer patients (P = 0.018)." (PMID 38900156, 2024). "For example, KRT5, KRT6A, KRT14, and DSG3 in LUSC25, and NKX2.126, SFTA227 in LUAD have been evidently proved directly correlated to the lung cancer diagnosis and progression." (PMID 40654610, 2025). "A number of the markers in this study had previously been reported as expressed as mRNA or protein in lung cancer: CAIX, CAXII, KK-LC-1, desmoglein 3, GPR87, Ly6/PLAUR domain-containing protein 3 and solute carrier family 7 member 11 protein." (PMID 29371917, 2017). "Five of these markers, CXorf61, DSG3, FAT2, GPR87, and LYPD3, were selected based primarily on their high and broad expression among the lung cancer samples relative to normal lung." (PMID 29371917, 2017). "For example, KRT5,KRT6A, KRT14, and DSG3 (All of these genes shown are with an adjustedp-value < 1e–200) in LUSC, and NKX2.1, SFTA2 (All of these genes shown are with anadjusted P-value < 1e–200) in LUAD have beenevidently proved directly correlated to the lung cancer diagnosis andprogression." (PMID 41347120, 2025).
bullous pemphigoid (8 papers, 2020 to 2025). Bullous pemphigoid (BP) is the most common form of autoimmune bullous dermatosis. "The absence of anti‐BP180/230 antibodies, which are typically elevated in bullous pemphigoid, contrasted with elevated anti‐desmoglein 1/3 antibodies (anti‐Dsg1: 171 U/mL; anti‐Dsg3: 172 U/mL), confirming the characteristic autoantibody profile of PNP." (PMID 41179602, 2025).
paraneoplastic pemphigus (8 papers, 2019 to 2025). Pemphigus is a group of chronic autoimmune skin diseases characterized by blisters formation on the outer layer of the skin and the mucous membranes. "Paraneoplastic pemphigus (PNP) is an autoimmune bullous disease associated with underlying neoplasms and characterized by antibodies against desmoglein 3 (Dsg 3) and plakins." (PMID 35911677, 2022). "Paraneoplastic pemphigus was unlikely due to the absence of mucosal involvement, desmoglein-3 antibodies, polymorphic lesions, or underlying malignancy." (PMID 41426874, 2025).
pancreatic cancer (7 papers, 2008 to 2025). "Using these approaches, we found that overall survival was the main clinical trait associated with the transcriptome profiles of pancreatic cancer patients, and that DSG3, ARNTL2, NUSAP1 and KRT7 were independent prognostic factors." (PMID 32081836, 2020). "An analysis of DSG3 in patients with pancreatic cancer (PC) revealed that it is correlated with clinical stage and that the higher the expression of DSG3 is, the worse the prognosis of PC patients." (PMID 40295497, 2025). "In this study, we used TCGA and GEO datasets to construct 5-mRNA signature (ANKRD22, ARNTL2, DSG3, KRT7, PRSS3) that is associated with the prognosis of pancreatic cancer patients." (PMID 36906533, 2023). "Our prognostic model containing four DEGs (DSG3, ARNTL2, NUSAP1 and KRT7) was used to determine the risk scores of pancreatic cancer patients, and patients with high risk scores were found to exhibit poor overall survival." (PMID 32081836, 2020). "The expression of Dsg1, Dsg2, and Dsg3 in pancreatic tissues was examined by immunohistochemistry and their expression in two pancreatic cancer cell lines, BxPC-3 and Panc-1, was determined by western blot analysis." (PMID 19091121, 2008). "High expression of EPYC, ANKRD22, ARNTL2, DSG3, KRT7, PRSS3 and MET predict poor prognosis of pancreatic cancer patients." (PMID 38184732, 2024). "In this study, a four-gene prognostic signature that included SPINK1, ANO1, DSG3, and GIMAP1 in patients with pancreatic cancer were identified." (PMID 33901011, 2021). "The comparative toxicogenomics database was used to search for drug molecules that could target DSG3, MET, and PLAU in pancreatic tumors, obtaining 4, 26, and 39 drug molecules, respectively." (PMID 39513120, 2024). "A machine learning based-study reported that the 5-gene signature including ANKRD22, ARNTL2, DSG3, KRT7, PRSS3 performed well on both our chosen training dataset and validation dataset and provided a new way to predict the prognosis of pancreatic cancer patients." (PMID 38184732, 2024).
melanoma (6 papers, 2016 to 2023). A malignant, usually aggressive tumor composed of atypical, neoplastic melanocytes. "Kaplan–Meier survival analyses showed that FLG, KRT5, DSG1, DSG3, and IVL expression levels were significantly associated with melanoma patient survival (p < 0.01)." (PMID 33178610, 2020). "Then, we identified 9 LR pairs (“BMP6- > HJV” 、"CCL8- > ACKR4” 、"DLL3- > NOTCH3"、"DSC3- > DSG3"、"GHRH- > GHRHR” 、"LRRC4B- > PTPRF"、"SEMA4D- > PLXNB1"、"SFRP1- > FZD6"、"UCN- > CRHR1′′) as key LR pairs in melanoma prognosis through Lasso Cox regression and Multiple Stepwise Regression." (PMID 36777724, 2023). "Five key genes FLG, DSG1, DSG3, IVL, and EGFR were identified in the TCGA database and melanoma tissues." (PMID 33178610, 2020). "In contrast, expression of other desmosomal cadherins (DSG1, DSG3, DSC1, DSC2, DSC3) was negligible, revealing that DSG2 is unique within this gene family for its expression in a large proportion of melanoma cell lines." (PMID 27340778, 2016). "The results suggested that FLG, DSG1, DSG3, IVL, and EGFR might play important roles and potentially be valuable in the prognosis and treatment of melanoma." (PMID 33178610, 2020).